CDK9 (cyclin dependent kinase 9)
Diseases named in the same sentence as CDK9 in open-access papers (continued):
Sharing a sentence is not in itself a finding about the gene and the disease.
chronic lymphocytic leukemia (16 papers, 2012 to 2025). "CDK9 is also responsible for transcription of anti-apoptotic factors, that belong to Bcl-2 superfamily: Mcl-1 (Myeloid cell leukaemia-1), Bcl-2 (B-cell CLL/Lymphoma 2), and XIAP (X-linked inhibitor of apoptosis), making CDK9 potential source of inhibition for anti-tumor purposes." (PMID 33805800, 2021). "Selective CDK9 inhibitors are in preclinical and clinical development and impressive anti-tumor activity has been observed in chronic lymphocytic leukemia cell lines." (PMID 27486754, 2016). "Flavopiridol (alvocidib), the first CDK inhibitor to enter clinical trials, is the most potent CDK9 inhibitor identified to date and has demonstrated marked anti-tumor activity in chronic lymphocytic leukemia (CLL)." (PMID 25277198, 2014). "In fact, the use of kinase inhibitor in clinical trials for the treatment of patients with chronic lymphocytic leukemia showed that the inhibition of CDK9- and CDK7-related pathways was responsible for the decrease of the antiapoptotic factor Mcl-1." (PMID 23840966, 2013). "Recently, the CDK9 inhibitor flavopiridol was shown to induce apoptosis in primary chronic lymphocytic leukemia by targeting CDK9, cyclin T1, AFF3/4 and MLLT1." (PMID 23140174, 2012). "Moreover, a core component of P-TEFb was identified as cyclin-dependent kinase-9 (CDK9)—a target in chronic lymphocytic leukaemia and necessary for MYC-mediated transcription regulation." (PMID 34681760, 2021). "Similarly, dinaciclib is a highly potent CDK inhibitor with selectivity for CDK1, CDK2, CDK5, and CDK9 in phase III clinical trials for the treatment of refractory chronic lymphocytic leukemia." (PMID 32412527, 2020). "In particular, a deregulated CDK9 pathway increases the expression of myeloid leukemia cell differentiation protein (Mcl-1), as shown by studies on biopsies obtained from patients with either advanced chronic lymphocytic leukemia or multiple myeloma." (PMID 23840966, 2013). "On the other hand, some CDK9 agents, such as dinaciclib, failed in phase III trials in chronic lymphocytic leukemia due to its toxicity profile, suggesting that the therapeutic index of these agents could be narrow." (PMID 35628286, 2022).
colon carcinoma (15 papers, 2018 to 2024). "A series of 2-amino-5-pyrimidine-thiazole derivatives, chemically similar to compound 2g, demonstrated potent anti-proliferative effects on MCF-7 cells and on HCT-116 colon carcinoma, as well as by inhibiting CDK9." (PMID 38139304, 2023). "In summary, CDK9 acts as a positive prognostic parameter at least in a subset of colon cancer patients." (PMID 36979907, 2023). "HCT116 colon cancer cells were exposed for 6 h to different doses of toyocamycin (50–500 nM) and to another CDK9 inhibitor (BAY1251152, 1–10 μM, 16 h) as control." (PMID 35884401, 2022). "We exposed HCT116 human colon cancer cells to 6 h toyocamycin treatment, which was sufficient to reduce CDK9 activity (as shown by a reduction in Phospho-Pol II level)." (PMID 35884401, 2022). "Effects of fadraciclib on CDK2 and CDK9 substrates were sustained to the end of the period tested (24 h) as was observed earlier in Colo205 colon cancer cells." (PMID 32645016, 2020). "Lnc-EPIC1 siRNA resulted in downregulation of MYC targets, including cyclin A, cyclin D and CDK9 in colon cancer cells." (PMID 33170148, 2020). "Optimized from the purine template of seliciclib, CCT068127 exhibits greater potency and selectivity against purified CDK2 and CDK9 and superior antiproliferative activity against human colon cancer and melanoma cell lines." (PMID 29063678, 2018). "While the levels of CDK2 and CDK5 in cells remained unchanged, indicating that the compound selectively degrades CDK9, this study suggests that strategies targeting CDK9 degradation may be useful in the treatment of colon cancer." (PMID 36142231, 2022). "In addition, the differences in cell type (B-cell lymphoma versus colon carcinoma) and source of analog-sensitive CDK9 (endogenously expressed versus excess of recombinantly purified) may provide further explanation." (PMID 31857848, 2019). "To see if CDK9 inhibitory antitumor effects are T-cell dependent, we implanted murine CT26.CL25 colon cancer cells into C57BL/6 mice and tested treatment with DAC and MC180295." (PMID 38172923, 2024). "MYC target proteins, including cyclin A, cyclin D and CDK9, were downregulated with Lnc-EPIC1 silencing, but upregulated after Lnc-EPIC1 overexpression in colon cancer cells." (PMID 33170148, 2020).
melanoma (15 papers, 2015 to 2025). A malignant, usually aggressive tumor composed of atypical, neoplastic melanocytes. "More recently, a study exploring the Rac1P29S mutation in melanoma cells proposed that cyclin-dependent kinase 9 (CDK9) plays a significant regulatory role in Rac1P29S activity." (PMID 40012016, 2025). "Furthermore, BRD4 inhibition was shown to reduce the interaction between BRD4 and CDK9 at the MYC locus and prevented the increase in MYC expression caused by i-CDK9 in HeLa, lung cancer, and melanoma cells." (PMID 34207158, 2021). "In vitro studies demonstrated that inhibiting CDK9 expression not only hindered the proliferation of Rac1P29S melanoma cells but also upregulated the surface expression of PD-L1 and MHC I proteins on tumor cells." (PMID 40012016, 2025). "In vivo experiments further revealed that combining a CDK9 inhibitor with a PD-1 inhibitor significantly suppressed the growth of Rac1P29S mutant melanoma." (PMID 40012016, 2025). "Compared to normal tissues, CDK9 overexpression and/or hyperactivity has been observed in several types of cancers (e.g., melanoma)." (PMID 35088192, 2023). "CDK9 has been reported to be overexpressed in many melanoma cell lines while CDKs 7 and 9 were also shown to be over-expressed in multiple uveal melanoma cell lines." (PMID 34062779, 2021). "More importantly, JQ1 also completely abolished the MYC induction by i-CDK9 in HeLa as well as the lung cancer cell line H1792 and the melanoma cell line A2058, whereas the control enantiomer was ineffective in this regard." (PMID 26083714, 2015). "To test the causal role of defective TE in the resistance to anti-tumor immune response, we chronically stimulated B16/F10 mouse melanoma cells with sublethal doses (25 nM) of flavopiridol, an inhibitor of the RNAP II elongation factor p-TEFb (Cyclin T/CDK9)." (PMID 30353012, 2018). "CSN6 was shown to interact with CDK9, stabilizing and protecting the latter from being ubiquitinated and subsequently degraded by UBR5 (Ubiquitin Protein ligase E3 component n-recognin 5), in the malignant melanoma cell lines A375 and MV3." (PMID 34062779, 2021). "The CDK9 PROTAC THAL-SNS-032 depleted cellular levels of CDK9 (and partly also other CDKs) in hESCs already at 1 μM concentration, presumably due to higher expression of CRBN ubiquitin ligase in hESCs compared to A375 melanoma." (PMID 32934219, 2020). "show that miR‐206 do not significantly affected CDK9 expression in melanoma 35, which suggested miR‐206 selectivity regulates CDK9 in distinct cancers." (PMID 28940993, 2017). "CYT-high primary melanomas on the other hand, did not have recurrent copy number amplifications above the threshold (Q value = 0.25), but rather had loses at 9p21.3 (CDKN2A/B), 9q34.11 (CDK9) and 16q24.2 (IRF8)." (PMID 33779796, 2021).
multiple myeloma (14 papers, 2013 to 2026). "In this study, we also demonstrated that combination of the BET PROTAC ARV 825 and the selective CDK9 inhibitor AZD 4573 synergistically caused significant growth inhibition of myeloma cells both in vitro and in an orthotopic xenograft model." (PMID 32559187, 2020). "Noteworthy, CDK9 inhibitors were tested only in pretreated patients with relapsed/refractory multiple myeloma or unfavorable cytogenetics." (PMID 35092513, 2022). "In the following part, we will discuss recent advances in the use of CDK9 inhibitors for multiple myeloma therapy." (PMID 35092513, 2022). "Multiple novel CDK9 inhibitors are currently used as either single agents or co-therapeutics in multiple myeloma." (PMID 35092513, 2022). "Short-hairpin RNA silencing of CDK9 in Multiple Myeloma (MM) cell lines reduced cell viability compared to control cells showing the dependency of MM cells on CDK9." (PMID 32559187, 2020). "Here, we observed that addition to inducing cell death, CDK9 inhibitors promoted the anti-myeloma activity of both proteasome inhibitors as well as BH3-mimetics, and that these effects were observed in both bortezomib-sensitive or -resistant cells." (PMID 28938651, 2017). "In the present study we have shown that the prototype of an emerging class of kinase inhibitors targeting both CDC7 and CDK9 kinases has cell death inducing activity in myeloma cellular models." (PMID 24202326, 2013). "We report that in all conditions myeloma cells undergo cell death upon PHA-767491 treatment and we report an overall additive effect with melphalan, bortezomib and doxorubicin, thus supporting further assessment of targeting CDC7 and CDK9 in multiple myeloma." (PMID 24202326, 2013). "All in all, combinations between CDK9 inhibitors and other myeloma targeted drugs (proteasome inhibitors) or cellular therapies [chimeric antigen receptor T cells] could be worthy explored." (PMID 37704591, 2023). "The activity and mechanism of action of the dual CDC7/CDK9 inhibitor PHA-767491 was assessed in a panel of multiple myeloma cell lines, in primary samples from patients, in the presence of stromal cells and in combination with drugs used in current chemotherapeutic regimens." (PMID 24202326, 2013). "Pembrolizumab in combination with dinaciclib (cyclin dependent kinase 9, CDK9 inhibitor) in patients with R/R CLL, DLBCL and multiple myeloma (MM) showed a ORR of 20-30% in patients with CLL and DLBCL whereas 0% in patients with myeloma." (PMID 38322418, 2024). "We examined the therapeutic potential of selective CDK9 inhibitors (AZD 4573 and MC180295) against human multiple myeloma cells in vitro." (PMID 32559187, 2020). "Therefore, CDK9 may represent a druggable target in myeloma having dysregulated MYC expression." (PMID 32559187, 2020). "Multiple Myeloma: Incubation of various multiple myeloma cell lines with seliciclib, a selective CDK2/E, CDK2/A, CDK7 and CDK9-inhibitor, resulted in apoptosis." (PMID 32380689, 2020). "However, the lack of clinical trials with CDK9 degraders in multiple myeloma makes the final comparison of these methods a matter of the future." (PMID 35092513, 2022).
pancreatic cancer (14 papers, 2017 to 2025). "In contrast, in pancreatic cancer, low CDK9 expression was associated with better survival, especially in patients with well-differentiated carcinomas." (PMID 36979907, 2023). "We recently showed that high CDK9 expression in pancreatic tumor tissue is associated with significantly shortened survival." (PMID 34535764, 2022). "This CDK9 mediated tumorigenic step has seen increasing attention within the literature and has been implicated in pancreatic cancer, hypopharyngeal carcinoma, leukemia, breast cancer, and hepatocellular carcinoma 13-17." (PMID 31892980, 2020). "CDK9 is a promising therapeutic target for the individualized therapy of pancreatic cancer, deserving of more preclinical and clinical research due to its ability to selectively target cancer cells and work in concert with conventional treatments." (PMID 40361480, 2025). "Previous studies from our research team have confirmed that CDK9 is highly expressed in pancreatic cancer tissues." (PMID 36979907, 2023). "For example, CDK9 can be highly expressed in pancreatic cancers, and when elevated, correlates to worse outcomes for these patients." (PMID 31892980, 2020). "Overall, new chemical entity based on symmetrical bis-pyrrolo[2,3-d]pyrimidines connected through di(ethylene-1,2,3-triazolyl)phenyl spacer was identified as a novel CDK9/cyclin T1 inhibitor for potential treatment of pancreatic cancer." (PMID 29104242, 2017). "Pancreatic cancer tissue shows overexpressed CDK9 and markedly reduced survival rates in patients." (PMID 40361480, 2025). "Further, CDK9 was found to regulate the expression of c-Myc and Mcl1, which are known to promote cell proliferation and survival, and CDK9 inhibition has been shown to interfere with c-Myc function in K-Ras mutant pancreatic cancers and hematologic cancer cells." (PMID 34359807, 2021). "We could recently demonstrate that the upregulation of CDK9 in human pancreatic cancer tissue negatively correlated with patients’ survival." (PMID 30340359, 2018). "P276-00, a CDK1, CDK4, and CDK9 inhibitor, could sensitise pancreatic cancer cells to gemcitabine-induced apoptosis." (PMID 30340359, 2018). "The combination of CDK9 inhibition and TRAIL treatment was reported to be highly efficient in various tumour entities, including NSCLC and pancreatic cancer." (PMID 38769311, 2024). "For instance, some key biomarkers have been exposed in pancreatic carcinoma, namely intercellular adhesion molecule 2 (ICAM2), anoctamin 9 (ANO9), proline-rich tyrosine kinase 2 (PYK2) and cyclin-dependent kinase 9 (CDK9)." (PMID 31412643, 2019). "CDK9 was shown to be overexpressed in PDAC tissue and the in vitro response of pancreatic cancer cell lines results in markedly reduced cell viability upon CDK9 inhibition." (PMID 30340359, 2018). "Indeed, it has been shown that CDK9 inhibition decreases the expression of short-lived anti-apoptotic factors cFLIP, cIAP1/2 and MCL-1 in a variety of tumour entities, including NSCLC, pancreatic cancer, colorectal cancer, and melanoma." (PMID 38769311, 2024). "CDK9 inhibition by SNS-032 might, therefore, pose a promising therapeutic approach for pancreatic cancer." (PMID 30340359, 2018). "Eventually, in vitro toxicity could be reported in a variety of cancer cell lines including pancreatic cancer by the inhibition of CDK2 and CDK9." (PMID 30340359, 2018).
lung carcinoma (12 papers, 2013 to 2026). "This statement seems to be true for bladder cancer and lung cancer, which are characterized by a high frequency of somatic mutations and in which low CDK9 expression correlates with a shorter overall survival time." (PMID 35326643, 2022). "Here we tested the efficacy of inhibiting cyclin-dependent kinase 9 (CDK9) on lung cancer cell lines with K-Ras and EGFR mutations and on lung cancer organoids." (PMID 34359807, 2021). "The CDK2/9 inhibitor CYC065 (where CDK2 > CDK9) treatment increased multipolar mitosis in lung cancer PDXs." (PMID 40232858, 2025). "Engineered over-expression of CDK2 or CDK9 was independently achieved by transient transfection of these respective expression plasmids within studied lung cancer cells, as confirmed by immunoblot assays." (PMID 38031910, 2023). "Immunofluorescent assays were performed in these CDK2 or CDK9 knocked-down lung cancer cells versus control transfected siRNAs." (PMID 38031910, 2023). "Here we show that inhibitors of the cyclin-dependent kinase 9 are highly effective in preventing the growth of a variety of lung cancer cell lines and lung cancer organoids with high potency." (PMID 34359807, 2021). "Since the addition of sublethal concentrations of the BRD4 inhibitor enhanced the efficacy of CDK9 inhibitors on lung cancer cells, we next examined if the combination treatment showed any additive effect on the apoptotic pathway." (PMID 34359807, 2021). "Three different CDK9 inhibitors reduced the viability and anchorage-independent growth of lung cancer cell lines at very low nanomolar to micromolar concentrations." (PMID 34359807, 2021). "Our results show that treatment with the CDK9 inhibitors induced cell death in the lung cancer organoids." (PMID 34359807, 2021). "Genome-wide CRISPRi screens identify factors that resensitize lung cancer cells to inhibition of CDK9 or MCL1." (PMID 31294695, 2019). "For example, compounds were identified that attacked specific proteins displaying vulnerability for EGFR-mutant cells (CD11A/B) yet also have effects on proteins (CDK9) that have generalized anti-tumor effects across lung cancer cell lines." (PMID 24189400, 2013). "Furthermore, a genome-wide CRISPR inhibition (CRISPRi) screen conducted in lung cancer cells demonstrated that knockout of CUL5, RBX2, or UBE2F (a specific E2 for CRL5 E3s) caused cells to become hypersensitive to a CDK9 inhibitor or MCL-1 inhibitor." (PMID 40699886, 2025). "Since CDK9 inhibitors could markedly reduce the viability of lung cancer cell lines cultured on tissue culture plates, experiments were conducted to assess if the inhibitors were effective in preventing adherence-independent growth as well." (PMID 34359807, 2021). "All together, these results show that CDK9 inhibition can significantly inhibit the growth of lung cancer cells, irrespective of their mutational status, and would help in overcoming the drug-resistance associated with the established therapies." (PMID 34359807, 2021). "CDK9 inhibitors could also significantly reduce the growth and viability of lung cancer organoids with high potency." (PMID 34359807, 2021). "As lung cancer is the leading cause of cancer mortality and most NSCLC patients develop resistance to first-line treatment, we performed genome-wide CRISPR inhibition (CRISPRi) screens in a NSCLC line resistant to both CDK9 and MCL1 inhibition." (PMID 31294695, 2019). "This is evident from the effect of CDK9 inhibitors on both K-Ras mutant and EGFR mutant lung cancer cell lines." (PMID 34359807, 2021). "Our results show that CDK9 inhibition significantly reduces the viability of K-Ras mutant (A549, H460, H23) and EGFR mutant (H1650, H1975, PC9) lung cancer cell lines at very low nanomolar to less than 0.5 μM concentration of CDK9 inhibitors, namely, AZD4573, LY2857785, and SNS032, respectively." (PMID 34359807, 2021).
lung carcinoma (continued). "In marked contrast, CDK9 knock-down did not exert statistically-significant effects on the appearance of chromosome rings or multipolar mitoses within human HOP62 or murine ED1 lung cancer cells." (PMID 38031910, 2023).